ANGPTL4 (angiopoietin like 4)
Diseases named in the same sentence as ANGPTL4 in open-access papers (continued):
Sharing a sentence is not in itself a finding about the gene and the disease.
cancer (continued). "In gene set enrichment analysis of differential gene expression in 445 normal colon tissue samples, ANGPTL4 loss-of-function was associated with down-regulation of several cancer-related gene-sets, providing mechanistic insight into anti-tumorigenic properties of ANGPTL4." (PMID 40511612, 2025). "Further suggesting a pro-tumorigenic function for ANGPTL4 in OC, immunofluorescence staining of Ki67, a widely used marker of cancer cell proliferation, indicated that ANGPTL4-deficient tumors exhibited much less Ki-67-positive cells than those in the sh-NC group." (PMID 38311733, 2024). "In cancer, ANGPTL4 is associated with the upregulation of NOX442 and NOX243 expression." (PMID 36782020, 2023). "Most recently, ANGPTL4 has been implicated in cancer cell migration, invasion, and metastasis." (PMID 38159259, 2023). "ANGPTL4 is overexpressed in several types of cancers and is associated with poor clinical outcome." (PMID 34708125, 2021). "Similar to the cytokine profiling results, most of the cancer‐associated proteins, such as ANGPTL4, KLK5, GAL3, VIM, HERs, CAPG, HO, CTSD, and AFP were produced at higher levels on the aged matrix, but were reduced to young matrix levels after LOX siRNA treatment." (PMID 34617419, 2021). "Here, we studied the link between ANGPTL4 and the risk of brain metastasis in cancer patients." (PMID 32405335, 2020). "ANGPTL-4 is induced by TGFβ-1 and is implicated in cancer metastasis." (PMID 33139674, 2020). "Despite plenty of evidence that has implicated the role of ANGPTL4 in cancer metastasis, the role of ANGPTL4 in vascular integrity remains unclear." (PMID 30049845, 2018). "The upregulation of genes encoding for soluble mediators of cancer progression, such as ANGPTL4 (angiopoietin-like 4), could be under the transcriptional control of the PPARβ/δ." (PMID 29966227, 2018). "Furthermore, ANGPTL4 increases cancer cell invasion and is part of gene expression signatures associated with distant metastasis in human cancer patients." (PMID 25968567, 2015). "ANGPTL-4 has been implicated as an important factor involved in energy homoeostasis, redox regulation, angiogenesis, the development of cancer and cachexia, and the development of metastasis and inflammation; however, the studies are still incomplete and often contradictory." (PMID 26508818, 2015). "Of note, angiopoietin-like 4 (ANGPTL4), a secretory protein encoded by a target gene of PPARs, triggers critical oncogenic processes such as inflammatory signaling, extracellular matrix derangement, anoikis resistance and metastasis, making it a potential drug target for cancer treatment." (PMID 33946986, 2021). "Altogether these findings shed light on a two‐step activation of ANGPTL4 by HIF2A and FURIN in senescent cells and its upstream role in promoting the proinflammatory SASP, cancer and potentially other senescence‐associated diseases." (PMID 41347893, 2026). "ANGPTL4 was previously reported to be upregulated in cancer cell lines by the HIF1A (Hypoxia Inducible Factor 1 Subunit Alpha) transcription factor during hypoxia." (PMID 41347893, 2026). "Angiopoietin‐like 4 (ANGPTL4) exhibits both pro‐ and anti‐tumorigenic roles in various cancers depending on the tissue context." (PMID 42028751, 2026). "As the SASP can participate in proliferation arrest, it is possible that the contribution of ANGPTL4 to this mechanism is mediated by its effect on the SASP during therapy‐induced senescence in cancer cells." (PMID 41347893, 2026). "The functions of ANGPTL4 in lipid metabolism regulation, angiogenesis, and vascular permeability make this protein an attractive target in cancer research." (PMID 40723247, 2025). "CAFs 1 communicated with cancer cells 3 located at the cancer zone A periphery through Angptl4-Sdc2 interactions, co-activating EMT and MAPK signaling pathways." (PMID 40723284, 2025). "We further performed a multivariate Cox regression analysis to solidify ANGPTL4’s role in cancer prognosis." (PMID 40233044, 2025).
cancer (continued). "Studies have shown that ANGPTL4 plays a diverse role in cancer development, progression, and dissemination." (PMID 40233044, 2025). "Single gene level analysis revealed that ANGPTL4 upregulated epithelial-to-mesenchymal transition (EMT) in 23 different cancers." (PMID 40233044, 2025). "Here we review the research into the function and role of ANGPTL4 in human diseases, with an emphasis on its role in cancer." (PMID 40723247, 2025). "We employed cis-Mendelian randomization and colocalization to evaluate the role of 5 lipid-perturbing drug targets (ANGPTL3, ANGPTL4, APOC3, CETP, and PCSK9) in risk of 5 cancers (breast, colorectal, head and neck, ovarian, and prostate)." (PMID 40511612, 2025). "The ANGPTL4 pathway operated through Angptl4-Sdc2 and Angptl4-Sdc4 interactions, where Angptl4-Sdc2 predominantly facilitated specific communication between CAFs 1 and cancer cells." (PMID 40723284, 2025). "Lastly, using the top 100 positively and negatively co-expressed genes, we conducted a GSVA analysis to explore the impact of ANGPTL4 on cancer related pathways." (PMID 40233044, 2025). "This study aims to summarize the role of ANGPTL4 in the literature by performing a pan-cancer meta-analysis of observational studies and establish an overall role for ANGPTL4 in cancer by conducting a comprehensive bioinformatics investigation." (PMID 40233044, 2025). "It primarily focused on the roles of ANGPTL4 in cancer, while other important areas, such as cardiovascular and metabolic diseases, received comparatively less coverage." (PMID 40723247, 2025). "The mechanistic connection between D-2HG and ANGPTL4 expression via m6A modification offers novel insights into the epigenetic regulation of cancer metabolism." (PMID 39910592, 2025). "Further work validating findings in human studies and clarifying potential mechanisms of effect will guide further assessment of the viability of ANGPTL4 inhibition as a therapeutic strategy for cancer prevention." (PMID 40511612, 2025). "In the TME,cytokines such as TGFβ and IL-6 have been shown to modulate ANGPTL4 expression in cancer cells." (PMID 40616161, 2025). "One study reported that ANGPTL4 prevents permeability and preserves vessel integrity, primarily in cancer." (PMID 40006981, 2025). "Over the past 25 years, significant efforts have been made in understanding the diverse roles of ANGPTL4 in lipid metabolism, angiogenesis, vascular permeability, inflammation, and cancer biology." (PMID 40723247, 2025). "Pan-cancer gene expression analysis revealed that ANGPTL4 was differentially expressed and upregulated in DLBC, GBM, KIRC, and UCS, while being downregulated in ACC, BRCA, ESCA, KICH, PRAD, READ, and STAD." (PMID 40233044, 2025). "This is further supported by our results where GSVA pathway enrichment showed that genes positively co-expressed with ANGPTL4 were positively correlated to EMT in 23 different cancers." (PMID 40233044, 2025). "In cancer zone A, Col1a2-Itga9/Itgb1 and Fn1-Cd44 interactions among cancer cells, along with Angptl4-Sdc2 signaling between CAFs 1 and cancer cells, collectively activated stromal remodeling and promoted EMT." (PMID 40723284, 2025). "Kaplan-Meier curves were graphed for cancers in which ANGPTL4 had a significant effect on OS, this included CESC, LGG, LUAD, MESO, ACC, STAD, and OV." (PMID 40233044, 2025). "To elucidate a more specific role for ANGPTL4 in different cancer types, we carried out single cell functional enrichment analysis for 11 different cancer types." (PMID 40233044, 2025). "We introduce the first comprehensive meta-analysis and pan-cancer bioinformatics study on ANGPTL4, aiming to unravel its implications across various cancer types." (PMID 40233044, 2025). "To further investigate the roles of ANGPTL4 in fibroblasts and cancer cells, we generated a CRISPR-based ANGPTL4-overexpressing SV-80 fibroblast cell line (referred to as OV_ANGPTL4)." (PMID 39811640, 2025).
cancer (continued). "The loss of ANGPTL4 in CAKi-1 cells led to significantly reduced cell migration, which is consistent with previous studies showing that ANGPTL4 can promote cancer cell migration." (PMID 39105498, 2024). "ANGPTL4 also contributes to EMT-mediated chemotherapy resistance by empowering cancer cells with metabolic flexibility." (PMID 38643448, 2024). "ANGPTL4 (or specific domains of the protein) can play roles of protecting against cancer or promoting tumorigenesis." (PMID 39022746, 2024). "It’s reported that ANGPTL4 facilitates the colonization of cancer cells to new tissues by increasing vascular permeability." (PMID 38643448, 2024). "Although these studies indicate a proangiogenic role for ANGPTL4 in cancers, an antiangiogenic role has also been suggested for ANGPTL4." (PMID 38212795, 2024). "Given its broad involvement in metabolic disorders, inflammation, and cancer, ANGPTL4 has potential as a therapeutic target, although further research is needed to clarify its diverse mechanisms." (PMID 39840089, 2024). "In particular, ANGPTL4, which involved in cancer progression and therapy resistance, was prominently upregulated both in our RNA sequencing analysis and GSE161097." (PMID 38643448, 2024). "The active PI3K/Akt pathway induces ANGPTL4 production in response to hypoxia, promoting cancer growth." (PMID 38791417, 2024). "These ANGPTL4-low cancers are characterized by the increased frequency of wild-type Von Hippel-Lindau(WT VHL), a gene that is commonly mutated in ccRCC, and an enrichment for genes associated with lipid metabolism." (PMID 39105498, 2024). "Currently, ANGPTL4 as a novel focal point for prognostic or predictive biomarkers across various malignancies and a burgeoning target in the realm of cancer therapies." (PMID 38992710, 2024). "In gastric cancer, the knockdown of ANGPTL4 suppresses cancer development, whereas, in breast cancer, contrasting results have been reported with either pro- or anti-tumorigenic effects." (PMID 39105498, 2024). "Overall, the role of ANGPTL4 in cardiovascular disease and lipid metabolism has been much better described than its roles in cancer." (PMID 37291514, 2023). "Protein kinase C (PKC)‐dependent phosphorylation of FMNL2 downstream of TGFβ stimulation is required for cancer cell invasion as well as ANGPTL4 vesicle trafficking and secretion." (PMID 36691769, 2023). "ANGPTL4 has been extensively studied in cancer research and reported to increase upon hypoxia and co-localize with HIF-1α." (PMID 38016947, 2023). "Scissor_C1 interacted significantly with CAF and endothelial cells, promoting cancer cell metastasis through ANGPTL4 secretion." (PMID 37091977, 2023). "One of the target genes of PPAR β/δ encodes for angiopoietin-like 4 (ANGPTL4), a secretory protein involved in angiogenesis, cancer progression, and metastasis." (PMID 37048084, 2023). "ANGPTL4 has a described role in known cancer pathways including its ability to regulate CREB, FOS, and STAT3 via ERK signaling." (PMID 37291514, 2023). "Some studies demonstrated that ANGPTL4 expression level also increased in patients with cancer, vascular pathologies, cardiovascular disease, and COPD." (PMID 37821811, 2023). "In fact, ANGPTL4’s role in cancer can be difficult to summarize because it has been shown to have both protective and promoting effects in different cancer types." (PMID 37291514, 2023). "Transforming growth factor beta (TGFβ)‐mediated secretion of Angiopoietin‐like 4 (ANGPTL4) is important for cancer development." (PMID 36691769, 2023). "Using RNAi technology and neutralizing Abs, we discovered that ANGPTL4 and STC1 differentially regulated cancer-associated mesothelial cell tumor-promoting functions, and that neutralization of ANGPTL4 alone or in combination with STC1 prevented metastasis." (PMID 36795484, 2023). "Cancer cell-derived ANGPTL4 was a TGFβ target in breast cancer, which was involved in the regulation of cancer growth, metastasis and angiogenesis." (PMID 35719975, 2022).
cancer (continued). "In a recent study, Angiopoietin-like 4 (ANGPTL4), which is known to upregulate cancer growth and metastasis, was found to accelerate the acinar to ductal metaplasia and eventual progression to PC, supporting the acinar origin of PC." (PMID 36421339, 2022). "ANGPTL4 is one of the protumorigenic proteins which can stimulate cancer cell growth and promote cancer metastasis." (PMID 36247876, 2022). "ANGPTL4 is an adipokine, a member of the angiopoietin-like protein family involved in angiogenesis regulation, lipid metabolism, cancer progression, and metastasis." (PMID 36430793, 2022). "This is consistent with previous studies showing ANGPTL4 is involved in the regulation of cancer and immune related diseases." (PMID 36153524, 2022). "Recent studies show that ANGPTL4 expression was dysregulated in various cancers and affects cancer progression." (PMID 35463073, 2022). "The collective data demonstrated that ANGPTL4 can be used as a potential marker for the prognosis of cancer patients." (PMID 34331381, 2021). "Growing evidence suggests a role of angiopoietin-like 4 (ANGPTL4) in cancer and stromal-epithelial communication." (PMID 33946986, 2021). "Similar to cancer cells, CrEL alone induced ANGPTL4 expression in PBMCs, monocytes, and lymphocytes from healthy human donors, and pretreatment with dexamethasone potentiated this effect." (PMID 34646996, 2021). "A tumorigenesis mice model with transplanted fibroblast cells and ANGPTL4 overexpressed CRC cells was established to investigate the effects of ANGPTL4 on the metastasis of cancer cells in vivo." (PMID 34405010, 2021). "A recent study indicated that ANGPTL4 exerts an angiogenic effect by promoting angiogenesis under hypoxic conditions to be involved in the development and progression of cancer." (PMID 34331381, 2021). "ANGPTL4 facilitates the extravasation of cancer cells, and LOX increases the migratory and invasive capacities of cells by activating the focal adhesion kinase (FAK)/AKT pathway." (PMID 34575983, 2021). "The complexity of ANGPTL4’s role in cancer genesis and development probably result from the alteration of cleavage and posttranslational modification." (PMID 32410376, 2020). "Extensive evidence demonstrates that angiopoietin-like 4 (ANGPTL4) is involved in the regulation of cancer growth, metastasis and angiogenesis." (PMID 32928141, 2020). "This evidence convinces us that the nickel-induced ANGPTL4 or other oxidative stress-respond protein via ROS/HIF-1α are the reason of cell transform into cancer." (PMID 31963541, 2020). "ANGPTL4 has been identified as an adipokine that regulates lipid metabolism and plays roles in cancer progression; however, there is still some controversy regarding its participation in cancer metastasis." (PMID 32641980, 2020). "Most of the studies have reported that ANGPTL4 plays major roles in cancer progression and development and it is involved in the regulation of energy metabolism, angiogenesis, metastasis, and anoikis resistance." (PMID 31963541, 2020). "Materials and Methods: From June 2015 to June 2016, serum samples from 113 cancer patients were prospectively collected, and ANGPTL4 concentrations were assessed." (PMID 32405335, 2020). "Recent researches revealed ANGPTL4’s wide‐spectrum of action including cancer growth, angiogenesis, metabolism, and metastasis." (PMID 32410376, 2020). "Contradictory results are reported for the role of angiopoietin-like 4 (ANGPTL-4) in the development of cancer-cachexia and inflammation, given its importance in angiogenesis and inflammatory signaling." (PMID 31741709, 2019). "Signal transducer and activator of transcription (STAT) 3 enriches cancer stem cell through upregulating ANGPTL4, and STAT3 inhibitor abrogated STAT3 binding to the ANGPTL4 promoter and exhibited anticancer activity." (PMID 31717924, 2019). "We thought that LMX1A increased the level of ANGPTL4, thus depress the expression of C-myc and reduce the cell proliferation of cancer cell." (PMID 31557193, 2019).
cancer (continued). "Several studies indicate that ANGPTL4 promotes cell proliferation, angiogenesis, anoikis resistance, and metastasis in some types of cancer." (PMID 31717924, 2019). "Accumulating evidence has shown that ANGPTL-4 plays a role in promoting metastasis by inducing the permeability of vasculatures in cancers that metastasise to the lungs, and that ANGPTL-4 can increase the frequency of venous invasion." (PMID 29795331, 2018). "ANGPTL4 empowered cancer cells metabolic flexibility during EMT, securing ample cellular energy that fuels multiple ABC transporters to confer EMT-mediated chemoresistance." (PMID 30342537, 2018). "Properly to its wide-spectrum of action, the roles of ANGPTL4 in human cancer are still controversial." (PMID 29389861, 2018). "Because the different roles of ANGPTL4 fragments, more studies to demarcate the different biological functions of cANGPTL4 and nANGPTL4 in cancer progression are urgently required." (PMID 29389861, 2018). "Despite the increasing emphasis on the differential roles of ANGPTL4 full-length, cANGPTL4, and nANGPTL4, the biological significance of each of them is still to be elucidated in cancer." (PMID 29389861, 2018). "Numerous published studies have signified that ANGPTL4 has an essential role in cancer onset, progression, metastasis, and anoikis resistance." (PMID 30049845, 2018). "The diverse roles of ANGPTL4 in human cancer are mainly attributed to its capability to target different cellular systems, such as cancer microenvironment, endothelial or metabolic cells." (PMID 29389861, 2018). "The complex mechanisms of action of ANGPTL4 gets to its possible clinical application as a promising candidate for clinical intervention against cancer." (PMID 29389861, 2018). "ANGPTL4 is also involved in energy homeostasis, redox regulation, inflammation, endothelial cell integrity, angiogenesis and development of cancer." (PMID 29389861, 2018). "ANGPTL-4 is involved in wound healing, cancer, angiogenesis and redox regulation, as well as lipid and glucose metabolism." (PMID 28978304, 2017). "The secreted protein angiopoietin-like-4 (ANGPTL4), which is induced by hypoxia, exerts diverse effects on cancer progression." (PMID 28894280, 2017). "Considering the similarities between the wound healing and cancer microenvironment, it becomes clear how the matricellular role of ANGPTL4 and its up- or downregulation can be translated in the neoplastic cellular context." (PMID 28182091, 2017). "Angiopoietin-like 4 is overexpressed in the hypoxic peri-necrotic regions of solid tumours and has central roles in cancer growth, anoikis resistance, angiogenesis, and metastasis." (PMID 28458654, 2017). "There are, however, few descriptions of ANGPTL4 in primary bone tumours or cancer metastasis to bone." (PMID 28458654, 2017). "ANGPTL4 is a TGFβ target gene in cancer cells and in vitro and in vivo experiments demonstrated that it impairs integrity of vascular endothelial cell layers fostering BC cell passage during lung metastatic process." (PMID 29287594, 2017). "Angptl4 is a positive acute phase protein which plays an important role in inflammation and cancer growth and metastasis." (PMID 26512722, 2015). "Another study has found that ANGPTL4 protein in carcinoma tissues is significantly lower than in adjacent tissues of HCC patients." (PMID 25148701, 2014). "ANGPTL4 is thought to play critical roles in cancer growth and progression, angiogenesis, and metastasis." (PMID 24260413, 2013). "Recent reports demonstrate that ANGPTL4 expression is upregulated in the majority of human cancers including ESCC." (PMID 23925665, 2013). "Given the multitude of evidence pointing to a role for ANGPTL4 in tumorigenesis, elucidating other molecular mechanisms necessary for cancer progression that are induced by this protein is worthwhile." (PMID 22481923, 2012).